KIF15 (kinesin family member 15)
Diseases named in the same sentence as KIF15 in open-access papers (continued):
Sharing a sentence is not in itself a finding about the gene and the disease.
glioblastoma (1 paper, 2024). The most malignant astrocytic tumor (WHO grade IV). "Prompted by above findings, we next explored the possibility that REST associates with P300 to co-regulate glioblastoma cell malignancy by synergistically targeting KIF15." (PMID 39430242, 2024). "Given the essential tumor-promoting role of KIF15 in glioblastoma cell survival, it is meaningful to delineate the underlying mechanisms controlling KIF15 expression." (PMID 39430242, 2024). "Together, all these data proved that KIF15 promotes glioblastoma progression under the targeted regulation of REST." (PMID 39430242, 2024). "We first searched the ChIP-seq data in Cistrome Data Browser and found that the KIF15 promoter region possesses highly activate state in human glioblastoma cells, which was indicated by the binding of H3K4me3 and H3K27ac." (PMID 39430242, 2024). "Consistently, a positive correlation between REST and KIF15 expression in glioblastoma tissues from TCGA database was observed." (PMID 39430242, 2024). "In order to evaluate the functions of KIF15 in glioblastoma progression, we first analyzed its expression based on clinical data from Oncomine and Human protein Atlas database." (PMID 39430242, 2024). "By analyzing the mRNA expression data (GSE4290) from GEO database, the expression of KIF15 was gradually up-regulated with the increase of pathologic grade in glioblastoma." (PMID 39430242, 2024). "We further acquired the overall survival information of glioblastoma patients with different KIF15 expression in TCGA&GTEx database, and the result showed that high KIF15 expression predicted poor outcomes in glioblastoma patients." (PMID 39430242, 2024). "Compared to normal tissues, we found that KIF15 was highly expressed in 12 different kinds of cancers, especially in glioblastoma." (PMID 39430242, 2024). "From the current research, our study at least provides a theoretical basis for the usage of KIF15-IN-1 in glioblastoma treatment." (PMID 39430242, 2024). "DNA pulldown assay confirmed that REST could bind to KIF15 promoter probe in different glioblastoma cells and such binding was alleviated upon REST silencing." (PMID 39430242, 2024). "We also analyzed the expression of KIF15 in different glioblastoma cell lines." (PMID 39430242, 2024). "First, REST has been found to be recruited to the KIF15 promoter and activate KIF15 transcription in GBM cells, which provides a deep understanding in the regulatory mechanism of KIF15's abnormal activation in glioblastoma." (PMID 39430242, 2024). "Considering the pivotal role of KIF15 in glioblastoma progression proved by us, whether KIF15-IN-1 could be used in anti-glioblastoma alone or in combination with other treatments, including chemotherapy or cell cycle suppression, should also be further investigated." (PMID 39430242, 2024). "Overall, our results showed the essential role of P300 and its HAT activity in the anchoring of REST at KIF15 promoter region and, most likely, in the regulation of REST on KIF15 expression in glioblastoma progression." (PMID 39430242, 2024). "Furthermore, we evaluated and found REST was highly expressed in different glioblastoma cells, and ectopic REST expression increased KIF15 expression in GBM cells, while REST knockdown reduced KIF15 protein level." (PMID 39430242, 2024). "More importantly, the simultaneous hyper-expression of P300/REST/KIF15 could effectively separate GBM tissue from normal brain tissues and high expression of these three simultaneously predict poor prognosis in glioblastoma patients." (PMID 39430242, 2024). "Since REST might be a potential regulator of KIF15 to be involved in the tumor-promoting role of KIF15 and no research focusing on the function of REST in GBM has been reported, we therefore next evaluated the intrinsic tumor-promoting role of REST in glioblastoma cells." (PMID 39430242, 2024).
Hyperinsulinemia (1 paper, 2024). An increased concentration of insulin in the blood. "Additionally, hyperinsulinemia inhibited the transcriptome required for cell cohesion MELK, CDCA7, ESCO2, mitotic spindle assembly KIF15, SGO1, and AURKB, and kinetochore formation KNL and NDC80." (PMID 39768214, 2024).
lentivirus infection (1 paper, 2023). Virus diseases caused by the Lentivirus genus. "On the 5th day after lentivirus infection, the apoptosis rate of shCtrl group and shKIF15 groups was detected by flow cytometry to explore the effects of down-regulation of KIF15 on cell apoptosis of DU 145 and PC-3 cells, showing significantly enhanced cell apoptosis in shKIF15 group (P < 0.01)." (PMID 37658042, 2023).
lung squamous cell carcinoma (1 paper, 2020). "It is interesting to note the WGCNA used to look for the hub gene that is correlated with miRNA, but the authors used samples from lung squamous cell carcinoma (LUSC) in the TCGA database and found another gene from the KIF family, KIF15." (PMID 32391047, 2020).
lymph node metastasis (1 paper, 2022). "Here, we observed that in KIF15 is significantly upregulated in tumors of patients with lymph node metastasis and distant metastasis." (PMID 36280663, 2022).
metastatic prostate carcinoma (1 paper, 2025). A carcinoma that arises from the prostate gland and has spread to other anatomic sites. "The eight genes where higher expression was associated with worse prognosis (CYC, CYP51A1, DHFR, EBP, KIF15, PPM1D, SQLE, and UMPS) represent potential additional therapeutic targets in metastatic prostate cancer." (PMID 40405591, 2025). "Eight genes (CYC, CYP51A1, DHFR, EBP, KIF15, PPM1D, SQLE, and UMPS) demonstrated strong dependency in cell lines and were also associated with worse prognosis clinically, representing potential therapeutic targets in metastatic prostate cancer." (PMID 40405591, 2025).
mood disorder (1 paper, 2025). A cognitive disorder a disturbance in which the person's mood is hypothesized to be the main underlying feature. "Our data uncover a novel function of KIF15 in synapses and also offer valuable insights into the pathogenesis of mood disorders." (PMID 40892874, 2025). "In this study, we found that Kif15-/- mice have exhibited significant impacts on dendritic morphology and function, which contributes to mood disorders." (PMID 40892874, 2025). "In our study, we found that KIF15 gene knockout mice exhibited mood disorder during the postnatal development." (PMID 40892874, 2025). "As a plus-end microtubule kinesin in neurons, Kif15 not only affects the growth of neuronal axons, but also mediates the expression and localization of postsynaptic protein in vivo, and then affects the mood disorders in mice." (PMID 40892874, 2025).
nasopharyngeal carcinoma (1 paper, 2022). A carcinoma arising from the nasopharyngeal epithelium. "Correlation between the expression level of KIF15 and clinicopathological characteristics of patients with nasopharyngeal carcinoma." (PMID 35359374, 2022). "However, there are few systematic evaluations on the role of KIF15 in human cancers, and the role of KIF15 in the diagnosis and prognosis of nasopharyngeal carcinoma (NPC) also remains unexplored." (PMID 35359374, 2022).
non-small cell lung carcinoma (1 paper, 2023). A group of at least three distinct histological types of lung cancer, including non-small cell squamous cell carcinoma, adenocarcinoma, and large cell carcinoma. "Overexpression of KIF15 promotes lung carcinogenesis and cancer cell proliferation and is associated with a poor prognosis in non-small cell lung carcinoma." (PMID 37777755, 2023).
pancreatic adenocarcinoma (1 paper, 2019). "The kinesin family member 15 (KIF15), which controls microtubule assembly and mitosis, activates the MEK/ERK axis, promoting pancreatic adenocarcinoma cell growth." (PMID 31117237, 2019).
prostate tumor (1 paper, 2021). "Overall, these data suggest that high protein levels of KIF15 correlated with increased EGFR protein levels in prostate tumor samples." (PMID 34804913, 2021).
uterine corpus endometrial carcinoma (1 paper, 2022). A endometrial carcinoma (disease) that involves the body of uterus. "Mutation status of KIF15 was evaluated, the highest alteration rate of KIF15 (8.13%) appears in patients with uterine corpus endometrial carcinoma with ‘‘mutation’’ as the primary type." (PMID 35359374, 2022).
viral infection (1 paper, 2021). "Several differentially expressed genes between the two trajectories (CTSG, PRC1, DEFA4, KIF15, TCEAL9, HMMR, CEP55, and AZU1) were overexpressed in patients with severe viral infection, but not in those with non-severe viral infection compared to HCs." (PMID 33765435, 2021).
tumor (42 papers, 2009 to 2026). "The results showed that REST overexpression partially alleviated tumor growth inhibition caused by KIF15 knockdown." (PMID 39430242, 2024). "Subsequently, the correlations between KIF15 and tumor mutation burden (TMB), microsatellite instability (MSI), and immune infiltration degree were investigated." (PMID 35359374, 2022). "The expression pattern, prognostic value, molecular function, tumor mutation burden, microsatellite instability, and immune cell infiltration of KIF15 were examined based on public databases." (PMID 35359374, 2022). "Meanwhile, subsequent mechanistic investigation identified that KIF15 might act on the classical PI3K/Akt signaling pathway to promote GBC development since treatment with an Akt activator could attenuate the anti-tumor impact induced by KIF15-deficiency." (PMID 38433242, 2024). "Additionally, KIF15 expression was related to cancer infiltration of immune cells, tumor mutation burden, and microsatellite instability." (PMID 35359374, 2022). "Recent studies demonstrate that KIF15 overexpression promotes tumor proliferation, invasion, and therapy resistance across various tumor types, including lung, breast, and pancreatic cancer." (PMID 41584727, 2026). "The results demonstrated that KIF15 knockdown significantly suppressed tumor growth and enhanced the efficacy of immunotherapy." (PMID 41584727, 2026). "Single-sample gene set enrichment (ssGSEA) analysis showed the high relevance of KIF15 to tumor proliferation, DNA replication, and the PI3K/Akt/mTOR pathway." (PMID 40087774, 2025). "KIF15 was found to be highly expressed in PCa tissues, correlating with tumor invasion depth and poor prognosis." (PMID 40740483, 2025). "Accumulating evidence suggests that KIF15 is often upregulated in multiple malignancies and plays a vital role in tumor progression." (PMID 40087774, 2025). "In vivo experiments further confirmed that KIF15 knockdown inhibited tumor growth in a mouse xenograft model, with downregulation of KIF15, p‐PI3K, and p‐Akt in the tumors." (PMID 40740483, 2025). "Other results have demonstrated that inhibiting KIF15 hinders tumor cells from developing resistance to KIF11 inhibitors." (PMID 38672404, 2024). "Western blot and IHC staining of tumor tissues proved that the decreased expressions of p-AKT and EMT- and cell cycle-associated protein markers mediated by KIF15 knockdown were also rescued by REST overexpression." (PMID 39430242, 2024). "In other words, KIF15 plays an integral role in the tumor-promoting function of REST in GBM, thereby indirectly proving the importance of KIF15 in GBM development." (PMID 39430242, 2024). "Above all, the results showed that the expression of KIF15 increased with the deepening of tumor malignancy, indicating its potential role in tumor development." (PMID 37658042, 2023). "We next investigated publicly available databases to assess the RNA expression of transcripts encoding for KIF11, KIF15, TPX2, and AURKA in EWS patient tumor samples using BioGPS (E-GEOD-12102)." (PMID 37894278, 2023). "Although not statistically significant, immunohistochemical analysis showed that tumor tissues in more advanced pathological stages were accompanied by higher KIF15 expression." (PMID 37658042, 2023). "KIF15, a member of the kinesin-12 family, regulates abnormal cell proliferation, tumorigenesis, and tumor invasiveness." (PMID 37266661, 2023). "KPNA2, BZW2 and KIF15 were involved in protein synthesis and transport and were suggested to be related to tumor progression." (PMID 37202800, 2023). "The results indicated that the expression of KIF15 upregulated in tumor tissues than in the adjacent normal tissues." (PMID 36807568, 2023). "In this study, we found for the first time that KIF15 promotes the glycolytic capacity of PC cells and PC tumor growth." (PMID 36807568, 2023). "Till now, the function of KIF15 in various types of human cancers has been reported, which was generally identified as a tumor promotor." (PMID 37658042, 2023).
tumor (continued). "During cell division, dysregulation of KIF15 can result in aberrant cell proliferation, tumorigenesis, and tumor aggressiveness." (PMID 35359374, 2022). "Accumulating evidence shows that KIF15 is involved in cell motility, integrin trafficking and cytoskeleton rearrangement of both normal and tumor cells." (PMID 36280663, 2022). "There is emerging evidence indicating that Kif15 plays vital roles in influencing the growth of axons and interference with the progression of the tumor." (PMID 35370541, 2022). "In the present study, a pan-cancer investigation was performed revealing that KIF15 played a vital role in prognosis, molecular function, signaling pathways, and tumor immunity in differ cancer types based on public databases." (PMID 35359374, 2022). "EX527 is a highly selective deacetylase SIRT1 inhibitor, and KIF15-IN is a highly selective inhibitor of KIF15, both of them are considered to have a significant inhibitory effect on tumor proliferation." (PMID 36280663, 2022). "The downregulation of KIF15 inhibits tumor growth by inhibiting proliferation, migration, inducing apoptosis and blocking cell cycle." (PMID 33985517, 2021). "KIF15 is mainly expressed in the cytoplasm of tumor cells and its expression was significantly higher in CRPC samples than in primary PCa samples." (PMID 34804913, 2021). "Through western blot analysis, the protein level of KIF15 was found to be higher in tumor tissues than that in paratumor tissues." (PMID 32549756, 2020). "Xenograft experiments reveal that downregulating KIF15 can inhibit GC tumor growth and promote GC apoptosis." (PMID 32322172, 2020). "In the present study, we clarified that expression of FANCB, KIF15, KIF4A, ERCC6L, and UBE2C are regulated by DNA methylation changes of their promoter CpGis and closely associated with tumor prognosis in HCC using the TCGA database." (PMID 32703154, 2020). "Tumor volume measurements in mice demonstrate that the sh-KIF15 group showed a slower increase in tumor volume compared with the sh-Ctrl group (P < 0.01)." (PMID 32322172, 2020). "We performed a series of biological experiments to further explore whether the anti-tumor properties of ATR-I were dependent on KIF15 downregulation." (PMID 40087774, 2025). "High KIF15 protein levels were also found to correlate with advanced tumour stage." (PMID 40002279, 2025). "Considering the essential role of KIF15 in cell mitosis 8, we deduced its tumor-promoting function in GBM might be realized by its regulation on cell cycle." (PMID 39430242, 2024). "Meanwhile, KIF15 knockdown could also restrain tumor proliferation and migration and enhance sensitivity to chemotherapeutic agents like staurosporine, 5-FU, and cisplatin." (PMID 38433242, 2024). "We then established a nude mouse model of subcutaneous tumor formation in vivo, and the results showed that interference with KIF15 expression could significantly inhibit the formation and growth of xenografts." (PMID 37658042, 2023). "Nude mice injected with overexpressed KIF15 PC cells increased tumor size." (PMID 36807568, 2023). "The results indicated that KIF15 overexpression accelerated tumor growth in PC-bearing nude mice." (PMID 36807568, 2023). "Finally, we sectioned the xenografts for immunohistochemistry to detect the effects of KIF15 on the expression of tumor proliferation index Ki67." (PMID 37658042, 2023). "Moreover, according to Mann–Whitney U-analysis, there was a significant positive correlation between the high expression of KIF15 and the depth of tumor invasion (T Infiltrate), which was further confirmed in Spearman rank correlation analysis." (PMID 37658042, 2023). "In short, our results suggest a likely regulatory role of KIF15 in tumor immunology." (PMID 35359374, 2022). "However, researches investigating the possible role of KIF15 in the regulation of tumor immunity are seldom." (PMID 35359374, 2022).